TTN (titin)
Diseases named in the same sentence as TTN in open-access papers (continued):
Sharing a sentence is not in itself a finding about the gene and the disease.
cancer (continued). "Changes in titin expression in breast, lung, colorectal, and gastrointestinal cancers have been strong indicators of its role in cancer development and progression." (PMID 39944242, 2025). "After Nab-PTX + pembrolizumab, MDSCs cocultured with TTN-KO cancer cells attenuated apoptosis and increased CD24 + CD44 + cell subpopulations in TNBC." (PMID 41326912, 2025). "Alterations in titin expression in breast, lung, colorectal, and gastrointestinal cancers have been strong indicators of its role in cancer development and progression." (PMID 39944242, 2025). "The fragmentation of titin protein into the urine titin N-terminal fragment has emerged as a promising biomarker for muscle damage, with recent investigations exploring its implications in cancer development and progression." (PMID 39944242, 2025). "To delve further into the impact of ALKBH1 mutations on STAD, we explored their interactions with other common genes involved in cancer progression, including TTN, PBRM1, and SETD2." (PMID 38317214, 2024). "While the involvement of the TTN gene in cancer biology remains contentious, emerging evidence suggests its immunological relevance." (PMID 37916187, 2023). "In drug sensitivity analysis, we found that low expression of these four genes (TTN, ARID1A, KDM6A, and RB1) was positively associated with resistance to cancer therapeutics response portal (CTRP)." (PMID 37065485, 2023). "To further confirm functional proteins associated with drug efficacy and response, we identified 19 genes as cancer-related genes (CRGs) in PCa, whereas 15 were overlapped DEP/Gs, and four (TTN, NBPF14, AHNAK2, COL1A1) were the top mutated genes in PCMR." (PMID 37121942, 2023). "The results verified six mutations in three genes, OBSCN, TTN, and RPGRIP1L, in at least one cancer type." (PMID 33597970, 2021). "Here we found that KLK6 high tumors carry mutations in two longest genes in the human genome, i.e., TTN, a structural protein in striated muscles and MUC16, which encodes the cancer antigen CA-125." (PMID 34065672, 2021). "It is not surprising to find associations between longer genes and cancer and heart pathologies often caused by mutations in particularly long genes, like DSC2 and TTN." (PMID 33643374, 2021).
cancer (continued). "More importantly, the high-risk patients were associated with decreased UBQLN4 expression, higher accumulation of immune cells, lower Titin (TTN) mutation frequency, worse immunotherapy efficacy, and cancer-associated pathways." (PMID 34761007, 2021). "Along this line, pathogenic Titin variants are frequent in patients with peripartum cardiomyopathy (PPCM;) who also have a 16-fold higher risk of cancer compared with age-matched healthy women in the normal (German) population." (PMID 32542459, 2020). "TTN and CAD were identified as mutated oncogenes; TTN ranks at the top of 518 potential protein kinase cancer genes and it encodes the largest polypeptide that is expressed in many functional cell types in oncogenesis." (PMID 30786925, 2019). "Other cancer causing candidates were SMURF2, PIK3AP1, RSBN1, TTN and SEMA6D, which were ranked in the top 25% potential drivers in transposon insertional mutagenesis studies in mice." (PMID 29854292, 2018). "The role of TTN as a cancer gene is currently a mathematically based prediction and will require direct biological evaluation." (PMID 26920143, 2016). "Benchmarking the results with TTN gene, we found that TTN is much less likely to be a cancer driver as predicted by LRT than the other two methods." (PMID 25112956, 2014). "Likewise, the TTN gene, identified in the mitotic spindle pathway, was proposed for “Enabling Replicative Immortality”, reflecting its contribution to the cancer cells’ ability to proliferate indefinitely." (PMID 40136626, 2025). "It is evident from the data that genes such as VHL, TTN, BAP1, PBRM1, and SETD2 are consistently identified as the most frequently mutated genes in KIRC, underscoring their potential importance as key drivers of tumorigenesis in this specific cancer subtype." (PMID 40649942, 2025). "Therefore, we proposed that TTN-inactivated cancer cells promoted MCT4 expression and regulated MDSC glycolysis via secreting DLL4." (PMID 41326912, 2025). "To assess whether TTN mutations affect the functionality of READ cells, we examined the cancer cell functions of TTN wild‐type (HCT116 WT/− and SW837 WT/WT) and TTN mutant type (HCT116−/MUT and SW837 WT/MUT cells) within 24 h." (PMID 39748197, 2025). "In the GBM dataset, CSNK2A1 and TTN are similarly identified as potential cancer genes as in NCG." (PMID 38510118, 2024). "A classic example of this is the TTN gene, one of the most frequently mutated genes across cancers simply due to its size, that does not contribute to oncogenesis." (PMID 38744952, 2024). "Changes in TTN expression or function within the tumor microenvironment could potentially influence the mechanical interactions between cancer cells, the extracellular matrix, and surrounding stromal cells." (PMID 37671167, 2023).
cancer (continued). "On further characterization of the immune microenvironment of TTN-mutant and wild-type cancers, TTN-mutant tumors showed higher levels of CD8+ T cell infiltration and immune checkpoint expression, which inferred the immune microenvironment differences of TTN mutants and TTN wild types." (PMID 36895786, 2023). "Previous reports indicated that MUC16 and TTN mutations could predict high TMB level and were correlated with favorable prognosis in pan-cancer, including GC." (PMID 38090588, 2023). "From the list of 20 FLAGS (FrequentLy mutAted GeneS) genes that are known to be frequently mutated in cancer but are unlikely to be pathogenic, TTN, AHNAK2, SYNE1, MUC16, and OBSCN were found among genes altered at ≥ 20% in mCLM." (PMID 38008721, 2023). "TTN mutation has been reported to be correlated with myopathy and cancer, and one study showed that lncRNA TTN-AS1, which is transcribed in the opposite direction of TTN, was upregulated in ccRCC samples and positive associated with poor clinicopathological performances." (PMID 37064095, 2023). "TTN, being a protein involved in muscle elasticity, may contribute to the mechanical properties of cancer cells or the surrounding stroma." (PMID 37671167, 2023). "Our results are consistent with previous findings and suggest that TTN may serve as a Prognosis therapeutic target in cancer." (PMID 36618928, 2022). "For TCGA, the top genes were known cancer genes such as TTN, MUC15, and PTEN." (PMID 35053577, 2022). "In the pan-cancer dataset, MUC16 and TTN mutations each showed significantly better OS30." (PMID 36127384, 2022). "Overall, the molecular characteristics of the TTN/OBSCN mutant phenotypes are of great significance for cancer therapy, particularly immunotherapy, and patients with the ‘Double‐Hit’ phenotype might benefit most from immunotherapy." (PMID 33624434, 2021). "The consequence revealed that the high- and low- METAscore groups exhibited distinct mutation characteristics and the genes with a high mutation frequency in TTN, MUC4, PIK3CA, and MUC16 which all correlated with EMT and critical cancer pathways including PI3K/AKT and JAK2/STAT3 in CESC." (PMID 34277697, 2021). "In addition, studies have reported that in the pan-cancer immunotherapy dataset, MUC16 and TTN mutations were associated with higher TMB and better OS." (PMID 34249711, 2021). "Although several reports have shown that urinary titin is an indicator of skeletal muscle atrophy, this is the first report to show that it predicts skeletal muscle atrophy after gastrointestinal surgery, which is one of the most invasive types of cancer resection." (PMID 40076646, 2025). "However, it is important to note that the expression of titin in cancer may be influenced by various factors, including genetic mutations, epigenetic changes, and alterations in the tumor microenvironment." (PMID 39944242, 2025). "Notably, mutations of TTN and MUC16 were associated with the TMB and could predict the immunotherapy efficacy in GC and pan‐cancer." (PMID 35621244, 2023). "Cancer cell viability was measured by Resazurin cytotoxicity assay and the gene and protein expression of APC, KRAS, TTN, HIF-1α, HIF-1β, and GLUT-1 were measured using rtPCR and ELISA." (PMID 41797969, 2026).
cancer (continued). "We found that patients with both MUC16 and TTN mutations had higher mortality risk than patients with neither mutation, and that patients with TTN mutations alone had an even higher mortality risk than patients with neither mutation, which differs from previous cancer literature." (PMID 39240165, 2024). "The second topology in the pseudo-albino skin comprised highly expressed cancer genes (Cyclin-Dependent kinases Protein (CDK), Chondrosarcoma Kinase (CDK4 cyclin-dependent kinase), Sarcomere protein titin (TTN), Tyrosinase Phosphatase (SHP2)." (PMID 39063015, 2024). "Outside of cancer field, SMYD2 has been reported to play a role in regulating titin stability in striated muscle." (PMID 39609254, 2024). "For NECE, five genes were mutated in 80% of patients, including PIK3CA, FAT3, MUC2, PLEC, and TTN, among which PIK3CA and FAT3 belong to the COSMIC Cancer Gene Census gene tier 1 and 2, respectively." (PMID 37920164, 2023). "In their comprehensive survey of 23 cancers in COSMIC data, TTN was ranked second highest in terms of numbers of somatic mutations." (PMID 32731431, 2020). "Among the eighteen genes, a specific oncogene, TTN (ENSG00000155657), has been regarded as a crucial marker for the distinction of six cancer subtypes and healthy controls." (PMID 29152097, 2017). "Collectively, our research indicates that TTN, GDF15, and MAPK14 can serve as prognostic biomarkers in female KIRC patients, offering prospects for enhanced treatment and patient outcomes in these cancers." (PMID 40854626, 2025). "While the involvement of titin in cancer is not as extensively researched as in neuromuscular disorders, previous studies suggest its potential importance." (PMID 39944242, 2025). "Following standard practice, known hypermutated genes such as mucins, titin, olfactory receptors, which are unlikely to play role in cancer, were removed." (PMID 32293263, 2020). "The TTN gene has not been studied extensively as a cancer-related gene in the literature but ranked third in our list." (PMID 33144687, 2020). "Interestingly, TCI revealed functional impact of certain SGAs with very high alteration frequencies, such as TTN, CSMD3, MUC16, RYR2, LRP1B, and ZFHX4, whose roles in cancer development remain controversial." (PMID 31276486, 2019). "It should be noted that among the most frequently mutated genes in our results, there are several constantly found mutated in cancer (e.g., PCLO, TTN) that are considered non-oncogenic." (PMID 29596374, 2018). "These are the Titin gene, TTN, and MLL3, which has been associated with other types of cancer, but not with BrCa." (PMID 24603726, 2014). "Moreover, CIBRA was able to identify the system-wide impact of all cancer genes evaluated and confirms that TTN does not have a system-wide impact in CRC, as also observed with the ML model." (PMID 39230704, 2024). "For a negative control we chose TTN, a known false‐positive in cancer resequencing studies." (PMID 34581028, 2021). "However, a recent study demonstrated that some network modules which confer significance in cancer subtyping are enriched for long genes such as TTN, which suggests that long genes should not necessarily be ignored by default in cancer gene studies." (PMID 27333808, 2016).
cancer (continued). "The relationship between ICAM1, TTN (Titin), and SYNE1 (Spectrin Repeat Containing Nuclear Envelope Protein 1) in cancer is not extensively studied, and their direct interplay in cancer is not well established." (PMID 37671167, 2023). "We also found that some of the identified genes, including TTN, MUC16, CSDM3, RYR2, USH2A, and SYNE1, are only altered in gynecological malignancies and not in other cancer types, highlighting their specific role in driving gynecological malignancies." (PMID 32626534, 2020). "Several genes with recurrent mutations were likely chance events, enhanced by their large size: DNAH11 (4516aa), TTN (34350aa), PIEZO1 (2521aa), TRPM6 (2022aa); none are thought to be involved in the pathogenesis of any form of cancer." (PMID 30256787, 2018). "For example, TTN is predicted as the third BRCA gene due to its long length, but it is not a cancer gene and therefore this is a false positive prediction." (PMID 29871594, 2018).